HYDIN (HYDIN axonemal central pair apparatus protein)
Description:
Required for ciliary motility (By similarity). Required for localization of SPEF2 to the ciliary axoneme in ciliated respiratory epithelial cells.
Synonyms: HYDIN1; KIAA1864; DKFZp434D0513; PPP1R31; CILD5
Tractability: Small molecule: it has a binding pocket of medium quality. PROTAC: ubiquitination databases record sites on it.
Gene: Protein-coding gene on chromosome 16 (70,802,084 to 71,230,722, reverse strand). Ensembl gene ENSG00000157423.
Subcellular location: Cell projection, cilium; Cytoplasm, cytoskeleton, cilium axoneme; Cell projection, cilium, flagellum
Subcellular location (Human Protein Atlas): Cytokinetic bridge; Cytosol; Equatorial segment; Primary cilium; Mitotic spindle; Nucleoplasm
Gene Ontology:
Biological process: axonemal central apparatus assembly; cilium movement
Cellular component: cilium; sperm flagellum; axonemal central apparatus; axoneme; axonemal central pair projection; motile cilium
Genetic constraint (gnomAD): Loss-of-function variants: 99 observed, 210.9 expected, observed/expected ratio (o/e) 0.47, 90% interval 0.4 to 0.56. The synonymous counts are far from expectation, so gnomAD's model fits this gene poorly and the ratio says little. Missense variants: 1,952 observed, 2,599 expected, observed/expected ratio (o/e) 0.75, 90% interval 0.72 to 0.78. Synonymous variants: 808 observed, 970.32 expected, observed/expected ratio (o/e) 0.83, 90% interval 0.79 to 0.88.
Gene-disease validity (ClinGen):
ClinGen rates the evidence that HYDIN causes each of these diseases.
primary ciliary dyskinesia 5 (autosomal recessive): Definitive. Any primary ciliary dyskinesia in which the cause of the disease is a mutation in the HYDIN gene.
Homologues: Orthologues: chimpanzee HYDIN (99% identical), macaque HYDIN (96% identical), dog HYDIN (82% identical), rabbit HYDIN (80% identical), rat Hydin (78% identical), mouse Hydin (78% identical). Paralogues in human: CFAP47 (11% identical), DLEC1 (6% identical).